CRP (C-reactive protein)
Diseases named in the same sentence as CRP in open-access papers (continued):
Sharing a sentence is not in itself a finding about the gene and the disease.
diabetes (continued). "Those with PSCI tended to be older (p = 0.003), had higher prevalence of hypertension (p = 0.039), diabetes (p = 0.001), DWI-ASPECTS 0–7 (p = 0.041) and WMLs (p = 0.012), and have higher NIHSS score (p = 0.041), and hyper-sensitive C-reactive protein levels (p = 0.001)." (PMID 40421099, 2025). "Biomarkers like interleukin-6 (IL-6), C-reactive protein (CRP), and tumor necrosis factor-alpha (TNF-α) are related to inflammation and may serve as indicators of cardiac inflammation in diabetes." (PMID 39129285, 2025). "Correlation analysis showed that acute IGF-II was correlated significantly with age (r = −0.16, p < 0.001), NIHSS (r = −0.12, p < 0.05), hs-CRP (r = −0.17, p < 0.001), and LDL (r = 0.11, p < 0.01), but not significantly with BMI, hypertension, insulin resistance, smoking, or diabetes." (PMID 40564988, 2025). "The baseline characteristics were balanced, as evidenced by the lack of statistically significant differences between the CRP groups in age, sex, hypertension, diabetes, smoking, and family history (p > 0.05)." (PMID 41200636, 2025). "The WHR, SBP, diabetes, LDL-C, and hs-CRP measurements correlated morewith female arteriosclerosis." (PMID 40026504, 2025). "Eighteen candidate predictors were initially evaluated based on clinical relevance and admission availability: sex, age, smoking history, alcohol consumption, hypertension, diabetes, SAP etiology, BMI, NEUT, PLT, HCT, D-dimer, CRP, IL-6, PCT, SIRS, APACHE II score, and NLR." (PMID 40852356, 2025). "Our study’s retrospective data set lacks key cardiovascular metabolic risk factors for diagnosing MASLD, like insulin resistance and C-reactive protein, and excludes diabetes patients and drug users." (PMID 40909451, 2025). "The current study showed that compared with the patients without PAD, those with PAD had a higher diabetes prevalence, smoking, and CRP levels." (PMID 40731833, 2025). "Those with CRP > 2 mg/L exhibited a higher likelihood of various conditions such as advanced age, obesity, smoking, lack of exercise, diabetes, hypertension, CAD, and HF, all of which are known to elevate the risk of AF." (PMID 41387931, 2025). "No notable differences in BMI, diabetes, or CRP levels were observed between the non-AMD and AMD groups." (PMID 41316464, 2025). "The age of the control group was lower than that of the NLM group, and the differences between the two groups in terms of age, history of diabetes mellitus, history of dysglycemia, history of smoking, fasting blood glucose, WBC, IL-6, and hs-CRP were statistically significant (P<0.05)." (PMID 40386528, 2025). "Advanced age, diabetes mellitus, chronic kidney disease, lack of prophylactic anticoagulation, and elevated levels of neutrophils, D-dimer, glucose, and CRP were identified as independent predictors of thromboembolic events." (PMID 41008724, 2025). "Participants with migraine were more frequently female, had higher education level, were overweight, had lower PIR, had increased CRP and eGFR levels, and had no hypertension, diabetes, or stroke, compared to those without migraine (all p < 0.05)." (PMID 40977107, 2025). "In unadjusted rough Cox regression model, age ≥ 75 years, type 2 diabetes mellitus, CKD stages 1–3, LAVI ≥ 40 mL/m2, NT-proBNP ≥ 1440 pmol/mL, hs-CRP ≥ 5.40 mg/L, adropin ≤ 2.95 ng/mL, sST2 ≥ 15.5 ng/mL were identified as the predictors for new onset AF in HFpEF patients." (PMID 40867615, 2025). "The participants with diabetes were also slightly older and had higher CRP and triglyceride levels compared with the participants without diabetes." (PMID 40962954, 2025). "The likelihood of delirium was estimated by calculating the total score for the presence or absence of diabetes, CRP values, and IL-6 severity at admission." (PMID 38523173, 2024). "When stratified by diabetes status, a significant inverse association between DASH-derived vegetable score and hs-CRP was observed in the non-DM group only." (PMID 38999806, 2024).
diabetes (continued). "Previous studies reported a strong and negative correlation between adiponectin serum levels and CRP in healthy individuals but also in patients with obesity, diabetes mellitus type 2, and metabolic syndrome." (PMID 39062875, 2024). "C-reactive protein was also significantly elevated in the diabetes group (54.32 ± 30.47 mg/L) compared to the non-diabetes group (31.74 ± 19.83 mg/L), with a p-value of less than 0.001." (PMID 39125561, 2024). "Furthermore, there were significant differences in the levels of diabetes-related markers such as LDH, FBS, D-dimer, CRP, serum creatinine levels, urea, and CPK." (PMID 39995847, 2024). "Several variables weresignificantly different, including sex, age, drinking, smoking, diabetes history,Cr, UA, HbA1c, TG, HDL-C, lymphocyte, albumin, CRP, angiotensin-converting enzymeinhibitor (ACEI), angiotensin receptor blocker (ARB), and proton pump inhibitors(PPI) (all p < 0.05)." (PMID 39076545, 2024). "There are statistical differences between two groups in age, race, marriage, education level, physical activity, BMI, hypertension, diabetes, CVD, CKD, COPD, cancer, use of cardiovascular drugs, WBC, neutrophil, CRP, aMED score, and HEI-2015 score (all P < 0.05)." (PMID 38956519, 2024). "However, among patients with diabetes, the accuracy of calprotectin increased to an AUROC of 0.94 (95%-CI = 0.89–0.99), while that of procalcitonin and CRP decreased to 0.90 (0.83–0.97) and to 0.87 (0.78–0.95)." (PMID 38755564, 2024). "Increased levels of CRP, IL-6, and TNF-α were also revealed in patients with both diabetes and MCI." (PMID 38396924, 2024). "There were also some increases in the average levels of D-dimer (1153 ng/mL) and CRP (63 mg/L) among individuals who did not have diabetes." (PMID 39995847, 2024). "However, significant differences were found among three groups in WBC, FBG, TC, TG, LDL-c, HDL-c, BUN, UA, NT-proBNP, Hs-CRP, Hcy, left ventricular ejection fractions (LVEF) and the presence of smoking, diabetes and hypertension." (PMID 38125618, 2024). "Additionally, a retrospective observational study performed in the United States revealed that those with diabetes had greater concentrations of LDH and CRP." (PMID 39995847, 2024). "In addition, biomarkers of inflammation, including high sensitivity C-reactive protein, various cytokines, and products of the complement pathway are elevated in humans with HTA, diabetes, cancer, COPD and asthma." (PMID 38498428, 2024). "Factors, including systolic blood pressure (SBP), serum triglyceride levels, C-reactive protein levels, age, weight, body mass index (BMI), waist circumference, MDA-oxLDL levels, and diabetes mellitus (DM) prevalence, were significantly higher in the aortic stiffness group." (PMID 39598185, 2024). "The similar outcomes were observed in model 2 (adjustment for age, gender, race) [1.93 (1.47, 2.54)] and model 3 (adjustment for age, gender, race, duration of diabetes, Glu, HbA1c, BUN, Albuminuria, Glb, Cr, SBP, TG, CRP, overweight, arthritis, CHD, stroke) [1.69 (1.25, 2.31)]." (PMID 38730329, 2024). "Non-survivors were older, had a higher frequency of diabetes, a shorter dialysis history, lower albumin, and also had increased hs-CRP and OPG levels." (PMID 39335504, 2024). "The results showed that HOMA for insulin resistance, but not LDL cholesterol or C-reactive protein, is the primary mediator linking triglycerides and diabetes." (PMID 38611646, 2024). "These variables were included in the multivariate logistic analysis, and it showed that the presence of diabetes mellitus and cryptogenic liver abscess, absence of splenomegaly, and CRP level were independent predictors for KPLA (all p < 0.05)." (PMID 39392039, 2024). "Some researchers found that CRP was a significant predictor of cardiovascular disease only among individuals without diabetes." (PMID 38570824, 2024).
diabetes (continued). "About the TyG quartiles, we found that elevated TyG levels significantly correlated with a higher likelihood of female participants, increased prevalence of hypertension, diabetes, elevated glucose, TG, diminished HDL-C, augmented LDL-C, and enhanced CRP levels." (PMID 38481325, 2024). "In a cross-sectional study that evaluated the circulating level of FABP4 in 43 morbidly obese and 38 lean women with no diabetes, there was a significant association between FABP4 and circulating CRP, HOMA-IR, and tumor necrosis factor (TNF)." (PMID 38731797, 2024). "Based on our analysis of 21 RCTs, we found that supplementing with L-carnitine can lead to significant improvements in various health markers, such as TG, LDL, FBG, HbA1c, HOMA-IR, CRP, TNF-α, weight, BMI, BFP, and leptin levels in patients with diabetes and glucose intolerance." (PMID 39085907, 2024). "However, during pre-diabetes, oxidative stress has been shown to activate pathways that release pro-inflammatory cytokines such as TNF-α, IL-6 and CRP." (PMID 39596174, 2024). "Univariate logistic regression analysis found that age, sex, SBP, hypertension history, diabetes history, CHD history, smoking history, drinking history, CRP, FPG, HbA1c, TC, LDL‐C, homocysteine, eGFR, uric acid, and, NLR were significantly related with Lacune." (PMID 38578037, 2024). "Three models were used: Model I (not adjusted for any covariates), Model II (adjusted for sex and age), Model III (adjusted for age, CRP, eGFR, sex; HDL-c, LDL-c, UA, CLD, PLT, Cystatin C; hypertension, HBA1C, diabetes; CKD, smoking, and drinking status variables)." (PMID 38402161, 2024). "Plasma C-reactive protein levels were found to be higher in patients with American cutaneous leishmaniasis (ACL −16.45 ± 7.35 mg/L), patients with type 2 diabetes mellitus (T2DM-28.55 ± 14.19 mg/L), and patients with both diseases (17.79 ± 7.41 mg/L) compared to the control group (5.94 ± 3.76 mg/L)." (PMID 39199338, 2024). "Compared to the low C-FAR group, patients in the high C-FAR group had higher values of WBC, FIB, CRP, FPG, UA, creatinine, and sodium and worse NYHA class, while they had lower values of RBC, hemoglobin, and GFR and a higher proportion of combined diabetes (all P values <0.05)." (PMID 39588387, 2024). "The serum levels of CRP were much higher in patients with diabetes, ranging from 2.2 to 325.0 (and creatinine ranged from 45.0 to 771.4) than in those without diabetes (CRP ranged from 1.0 to 224.0; creatinine ranged from 42.0 to 663.0)." (PMID 38792970, 2024). "Furthermore, significant variations were observed between the four groups regarding the occurrence of diabetes, hypertension, and hyperlipidemia and levels of blood glucose, HbA1c, HDL‐c, UA, CRP, and BMI (p < .05)." (PMID 38680023, 2024). "In the next steps, CRP, LMR, BMI, and diabetes were rejected." (PMID 39335569, 2024). "Univariate logistic regression analysis showed that age, sex, SBP, hypertension history, diabetes history, CHD history, smoking history, drinking history, SBP, CRP, FPG, HbA1c, TC, LDL‐C, homocysteine, eGFR, uric acid, and NLR were significantly associated with CSVD." (PMID 38578037, 2024). "In the Cox regression analysis, the final multivariable analysis revealed that male sex, BMI, hypertension, diabetes mellitus, TOAST classification, anemia, leukocytosis, CRP, decreased eGFR, white matter changes, and CMBs were associated with the recurrent group." (PMID 39407804, 2024). "Despite this, there was no significant change in the inflammatory biomarker CRP, or the inflammatory cytokines IL-6 or TNFα, in agreement with other vitamin C/antioxidant intervention studies in obesity and diabetes." (PMID 38671852, 2024).
diabetes (continued). "After adjusting for confounding factors (age, male, BMI, smoking, hypertension, diabetes, WBC, Neu, PLT, CRP, Alb, BUN, lactate, APACHE II score, and SOFA score), the results indicated that an increase of either 1 unit or 1 SD in DLR was significantly and positively correlated with AKI occurrence." (PMID 39877653, 2024). "The diabetes group had significantly higher average serum levels of CRP than the group without diabetes (p = 0.008)." (PMID 38792970, 2024). "ED subjects were prone to have lower educational level, higher CRP, and more likely have hypertension/diabetes than men without ED." (PMID 38760760, 2024). "Increased levels of C-reactive protein (CRP), TNF-α, and IL-6 have been observed in diabetes." (PMID 39295999, 2024). "Patients who have diabetes or are obese experience persistent, mild inflammation characterized by elevated levels of inflammatory markers such as tumor necrosis factor alpha (TNF-α) and C-reactive protein (CRP)." (PMID 39031306, 2024). "They identified increased levels of CRP values in association with a negative postoperative outcome in patients, with an association between CLTI and diabetes." (PMID 38672153, 2024). "In line with previous studies, we found that increasing age, female sex, presence of COPD and rheumatic disease, absence of diabetes mellitus, low CRP, and low BMI were independent predictors of higher adiponectin levels, whereas the CURB-65 score was not." (PMID 38633314, 2024). "Median plasma CRP was 2.1 mg/L in individuals with type 2 diabetes and 1.4 mg/L in individuals without diabetes (p = 7 × 10− 264) (a)." (PMID 38730445, 2024). "Inflammatory biomarkers, such as C-reactive protein (CRP) and interleukin-6 (IL-6), serve as indicators of the inflammatory state and have the potential to aid in predicting the likelihood of developing diabetes and experiencing cardiovascular complications." (PMID 37724233, 2023). "Maternal diabetes mellitus, initial FiO2 value, invasive ventilation, acidosis, hypochloremia, C-reactive protein level, patent ductus arteriosus and Gram-negative respiratory culture were independent risk factors for BPD severity." (PMID 36357648, 2023). "Whereas some other studies did not exclude individuals with elevated baseline CRP levels above 10 mg/L,34 36 which might have uplifted the exposure level due to the potential underlying issues of acute inflammatory condition other than the risk associated with diabetes development." (PMID 37775289, 2023). "Finally, Age, gender, smoking, hypertension, diabetes, LVEF, serum CRP, TC, LDLC and HDLC levels, rs2910164 CG and rs2910164 GG were included to construct a multifactorial logistic regression equation." (PMID 37189131, 2023). "The 10 most frequently occurring predictor variables in this review were as follows: LVEF (14/23), age (12/23), Killip classification (8/23), diabetes (7/23), Cr/eGFR (7/23), BNP/NT-proBNP (6/23), gender (5/23), cTnI (5/23), smoking (4/23), hypertension (4/23), and CRP/hs-CRP (4/23)." (PMID 38259313, 2023). "The fully adjusted model adjusts for age, race, education level, marital status, ratio of family income to poverty, BMI, smoking status, alcohol use, creatinine, CRP, glycohemoglobin, HDL, triglyceride, high blood pressure, coronary heart disease, diabetes, and stroke." (PMID 38111604, 2023). "Serum vitamin D was significantly lower, and serum CRP was significantly higher in adults with periodontitis with diabetes compared to individuals without diabetes." (PMID 38201914, 2023). "Compared with patients in Q1, patients with higher TyG-BMI levels were older; had a higher incidence of diabetes, CVD, and hypertension; had a higher proportion of males; and had increased urine output and higher TC, LDL-C, uric acid, and hs-CRP levels but lower DBP and HDL-C levels (P < 0.05)." (PMID 37670344, 2023).
diabetes (continued). "It is true, however, that a patient with systemic lupus erythematosus, complicated diabetes mellitus, or even simply CKD may have elevated CRP for other reasons." (PMID 36830901, 2023). "C-reactive protein levels were also significantly elevated in patients from subgroup 1 (average value 91 mg/L vs. 40.2 mg/L in the group without diabetes) (p = 0.0022)." (PMID 37627906, 2023). "According to the linear regression univariate analysis, the ECW/TBW ratio was positively correlated with male sex, age, history of diabetes and CVD events, log-transformed CRP (Log CRP), CTR, and simple PEW score and was negatively correlated with phosphorus level, Alb level, Cre/BSA, and nPCR." (PMID 37652929, 2023). "C-reactive protein (CRP) may reflect inflammation occurring in the progression of metabolic conditions, such as diabetes." (PMID 37834362, 2023). "BMI, smoking, diabetes, and CRP explained the KP abnormalities in the Obese group but not in the Depressed and COPD groups." (PMID 36986451, 2023). "The considered covariates for adjustment included demographic and behavioral factors such as sex, marital status, educational attainment, geographic location, smoking habits, and alcohol consumption, along with diseases history like presence of diabetes, hypertension, LDL-C, and CRP levels." (PMID 37337187, 2023). "The association between E3 and QA did not change when adjusting for diabetes, BMI, CRP, and smoking, indicating a direct effect of E3 on the KP or an effect via other mediators." (PMID 37895304, 2023). "Patients with higher age, lower HCT, lower albumin, lower CREAT, higher CRP, lower NPCR, higher IDWG, higher ferritin, higher phosphorous, higher WBC, presence of diabetes, lower potassium, lower BMI, low RRF, and lower pre and post weight have a higher chance of mortality in the following 3 years." (PMID 36403633, 2023). "Compared to male patients, female patients were older; had less frequent hyperuricemia, STEMI, current smoking; had more frequent CKD, hypertension, dyslipidemia, diabetes mellitus; had higher LVEF, platelet, HbA1c, CRP, AST, total cholesterol level; and had lower BMI and SUA levels." (PMID 36815018, 2023). "Patients with poorer diabetes control (higher HbA1c levels) tend to have elevated levels of lipids (e.g., cholesterol, triglycerides, LDL-C, sd-LDL, and cholesterol ratio), inflammation (hs-CRP), and hyperglycemia-related derangements (AGEs)." (PMID 40303237, 2023). "In patients without diabetes, elevated C-reactive protein levels are related to the future development of insulin resistance and type 2 diabetes." (PMID 37298118, 2023). "Patients who experienced poor outcome were more likely to be older and female and to have a higher incidence of atrial fibrillation as well as diabetes mellitus, NIHSS score at admission, international normalized ratio, fibrinogen, D-dimer, hemoglobin and C-reactive protein level (p < 0.05)." (PMID 36875705, 2023). "C-reactive protein levels were also increased in the study group vs. the group without diabetes (59.9 mg/L vs. 39.2 mg/L, p = 0.008)." (PMID 37627906, 2023). "A higher ECW/TBW ratio and PEW were independently associated with elevated risks of all-cause death even after adjustment for sex, age, hemodialysis durations, history of diabetes and CVD events, and CRP (adjusted HR [aHR]: 3.63, 95% CI 2.18–6.06, p < 0.0001; aHR: 1.79, 95% CI 1.10–2.90, p = 0.018)." (PMID 37652929, 2023). "One study confirmed our results among adults with diabetes and found that both LPA and MVPA could reduce biomarkers including C-reactive protein and triglycerides." (PMID 37810111, 2023). "The endpoints for the first one were CRP, TAC, MDA, NO, and GSH among individuals with T2DM, while the studied outcomes for the other one were TNF-α, CRP, IL-6, and NO among subjects with diabetes." (PMID 36239789, 2023).